FOXI2 (forkhead box I2)
Description:
Possible transcriptional activator.
Synonyms: FLJ46831
Tractability: No criterion of Open Targets' tractability assessment is met for any kind of drug.
Gene: Protein-coding gene on chromosome 10 (127,737,185 to 127,741,183, forward strand). Ensembl gene ENSG00000186766.
Subcellular location: Nucleus
Gene Ontology:
Molecular function: DNA-binding transcription factor activity, RNA polymerase II-specific; RNA polymerase II cis-regulatory region sequence-specific DNA binding; DNA-binding transcription factor activity; sequence-specific DNA binding
Biological process: anatomical structure morphogenesis; cell differentiation; regulation of transcription by RNA polymerase II; regulation of DNA-templated transcription
Cellular component: chromatin; nucleus
Genetic constraint (gnomAD): Loss-of-function variants: 18 observed, 11.19 expected, observed/expected ratio (o/e) 1.61, 90% interval 1.08 to 1.94. The synonymous counts are far from expectation, so gnomAD's model fits this gene poorly and the ratio says little. Missense variants: 541 observed, 397.39 expected, observed/expected ratio (o/e) 1.36, 90% interval 1.27 to 1.46. Synonymous variants: 240 observed, 184.35 expected, observed/expected ratio (o/e) 1.3, 90% interval 1.17 to 1.45.
Homologues: Orthologues: chimpanzee FOXI2 (98% identical), macaque FOXI2 (92% identical), guinea pig FOXI2 (76% identical), pig FOXI2 (76% identical), mouse Foxi2 (71% identical), dog FOXI2 (69% identical), rat Foxi2 (69% identical), tropical clawed frog foxi2 (49% identical). Paralogues in human: FOXI3 (49% identical), FOXC2 (28% identical), FOXC1 (28% identical), FOXD3 (27% identical), FOXD1 (27% identical), FOXD2 (26% identical), FOXE3 (26% identical), FOXA1 (26% identical), FOXA2 (26% identical), FOXL2 (25% identical), FOXS1 (25% identical), FOXL1 (25% identical), and 29 more.
Diseases named in the same sentence as FOXI2 in open-access papers:
FOXI2 is named in the same sentence as 12 diseases in open-access papers, as found by Europe PMC text mining. Sharing a sentence is not in itself a finding about the gene and the disease. The quoted sentences say what the papers report.
colorectal cancer (3 papers, 2014 to 2021). A primary or metastatic malignant neoplasm that affects the colon or rectum. "FOXI2 is a forkhead binding gene associated with transcriptional activation which has been seen to be consistently hypomethylated in colorectal cancer and REX1BD (required for excision 1 binding domain) is a putative DNA repair gene." (PMID 33632293, 2021). "FOXI2 methylation may be associated with increased risk of oral and colorectal cancers." (PMID 32633782, 2020). "For other genes, e.g. FOXI2 and SOX21, their methylation in colorectal cancer has not previously been reported, but they are likewise supported by Infinium Human Methylation 27 K microarray data from the TCGA consortium." (PMID 24485021, 2014).
metastatic prostate carcinoma (1 paper, 2022). A carcinoma that arises from the prostate gland and has spread to other anatomic sites. "Almost all of the FOX genes were differentially expressed in prostate cancer, prostate carcinoma, and metastatic prostate cancer, except FOXA3, FOXB2, FOXC2, FOXI2, FOXI3, FOXP4, and FOXR1." (PMID 36292640, 2022).
rectal cancer (1 paper, 2016). A primary or metastatic malignant neoplasm that affects the rectum. "Ten of the 36 (EYA4, FOXI2, CNRIP1, SFRP1, ADHFE1, C2orf40, MAL, PHACTR3, SST, TMEFF2) were known as rectal cancer related genes with aberrant methylation." (PMID 27566576, 2016).
Stroke (1 paper, 2022). Sudden impairment of blood flow to a part of the brain due to occlusion or rupture of an artery to the brain. "In line with our results, hsa-miR-574-5p was found to be downregulated in stroke patients and has been proposed as a biomarker for stroke diagnosis, while single nucleotide polymorphisms (SNPs) in one of its targets, FOXI2, has been identified as a risk factor for large vessel ischemic stroke." (PMID 35328807, 2022).
FOXI2 also shares sentences with these, for which no sentence is quoted: tumor (2 papers); adenoma (1); Anophthalmia (1); cancer (1); coloboma (1); lung carcinoma (1); microphthalmia (1); prostate carcinoma (1).